ALB (albumin)
Diseases named in the same sentence as ALB in open-access papers (continued):
Sharing a sentence is not in itself a finding about the gene and the disease.
cancer (continued). "Elevated ALB is often associated with better survival in cancer patients." (PMID 35965687, 2022). "Decreased albumin level is associated with malnutrition and cancer progression." (PMID 36458178, 2022). "ALB is closely associated with inflammatory and dystrophic status in cancer patients." (PMID 35663321, 2022). "Higher reduction in albumin level in cancer cases associated with death." (PMID 35350203, 2022). "In addition, a systematic review shows that high serum albumin concentration is associated with higher survival outcomes of cancer patients." (PMID 35392884, 2022). "Moreover, cancer-related systemic inflammation also results in loss of weight and cell mass, ultimately reflected by a lower BMI and decreased levels of serum albumin." (PMID 36297021, 2022). "Cancer survival studies that used PNI or NRI calculated by a nutrition-related biochemical marker such as albumin and total lymphocyte count (TLC) or weight loss reported that PNI or NRI might be a potential prognostic factor for cancer prognosis." (PMID 36396994, 2022). "Our study demonstrated that several clinical variables, including age, time from injury to surgery, COPD, albumin, hemoglobin, history of malignancy, and perioperative blood transfusion, were associated with 1-year post-operative mortality in geriatric Chinese HF patients." (PMID 35646950, 2022). "A lower serum albumin has been associated with poor survival of patients with cancer." (PMID 35847869, 2022). "As a result, the measure of the pre-treatment serum ALB level might be utilized in clinical trials to better identify cancer patients' baseline risk." (PMID 36531036, 2022). "In addition, pretreatment serum albumin levels provide prognostic significance and risk stratification in cancer patients." (PMID 36295649, 2022). "On the other hand, decreased serum albumin may be due to increased capillary permeability caused by cancer-related inflammation resulting in albumin escape into the interstitium and absorption by cancer cells, decomposition and utilization." (PMID 35571914, 2022). "Cancer-induced reprogramming of the host's glucose metabolism may cause insulin resistance and further decrease the serum albumin production." (PMID 36046647, 2022). "The C-reactive protein to albumin ratio (CAR) is associated with poor prognosis in various cancers." (PMID 36397047, 2022). "The cause of low hemoglobin and albumin levels in cancer patients is likely multifactorial." (PMID 35804906, 2022). "Hence, low levels of ALB in patients with different malignant tumors have been associated with poor prognosis, which was consistent with our results." (PMID 35719922, 2022). "We aimed to explore whether body mass index (BMI) and albumin were associated with overall survival (OS) in individuals who underwent pancreaticoduodenectomy (PD) for cancer." (PMID 35773692, 2022). "Moreover, we conducted sensitivity analyses–excluded patients with cancer, the results showed that albumin-corrected calcium was still positively associated with 30-day in-hospital mortality in the fully adjusted model (OR=1.1, 95% CI 1.0–1.1, P=0.005)." (PMID 36619536, 2022). "Serum albumin is known to be associated with prognosis in various cancer types." (PMID 33957727, 2021). "Taken together, albumin was supposed to be associated with cancer risk." (PMID 34041866, 2021). "Therefore, cancer type risk group, lactate dehydrogenase, and albumin were added to the primary prediction model." (PMID 34439240, 2021). "It was supposed that a lower level of serum albumin associated with higher cancer risk may indicate the influence on nutrition intake before cancer diagnoses." (PMID 34041866, 2021). "Although serum albumin level is used to evaluate protein reserves, this parameter also has been related to survival time in advanced cancer patients, overall survival in older cancer patients and risk of early death." (PMID 33920250, 2021).
cancer (continued). "Taken together, the positive results in our analysis could only indicate the association between serum albumin and cancer risk." (PMID 34041866, 2021). "Additionally, we observed a significant linear relationship between serum albumin concentrations and cancer risk." (PMID 34041866, 2021). "Lower serum albumin levels indicated an increased nutritional risk for malignant tumor patients." (PMID 35096561, 2021). "Importantly, patients with higher CL0 and poorer survival developed clinical features of cancer cachexia including increased weight loss and reduced serum albumin levels." (PMID 34514376, 2021). "Many studies proved the prognostic value of serum albumin and lymphocytes in malignant tumors: lower albumin levels were linked to poor prognosis for cancer patients, and high levels of lymphocytes may indicate a better prognosis." (PMID 35096561, 2021). "Thus, it is neither sufficient nor precise to evaluate patients' nutritional risk with regard to their cancer prognosis and treatment efficacy only by their BMI or albumin status." (PMID 35096932, 2021). "For decades, it has been confirmed that albumin was associated with the overall mortality, and especially the prognosis of cancer, whereas only a few studies were conducted concerning cancer risk." (PMID 34041866, 2021). "In addition, low levels of serum albumin reflect systemic inflammation, which is significantly associated with cancer progression." (PMID 34473762, 2021). "This study provides evidence that albumin may be valuable to the prediction and stratification of cancer risk in the general population." (PMID 34041866, 2021). "Though few studies explained the mechanism of the influence of serum albumin on cancer risk and mortality, a previous study conducted among dialysis patients suggested that the influence of serum albumin on mortality was partly explained by the inflammatory pathway." (PMID 34041866, 2021). "Since ALB levels are associated with many factors, such as stress, liver insufficiency, and changes in body fluid volume, their clinical utility for predicting cancer patient prognosis is limited." (PMID 34631767, 2021). "Although the association between endogenous antioxidants and cancer progression remains unclear, a previous study demonstrated that loss of albumin resulted in a plasma redox imbalance and promoted cancer growth and metastasis." (PMID 34473762, 2021). "Another study found that low levels of hemoglobin, albumin, and lymphocytes may be an important risk factor for recurrence-free survival and overall survival in postoperative cancer patients." (PMID 34249995, 2021). "Our present results showed that routinely measured inflammatory biomarkers (albumin and CRP) and combinations thereof (the GPS, the mGPS, and the CRP/albumin ratio) were respectively and independently associated with one-year mortality in older cancer patients." (PMID 34944774, 2021). "These indexes use different combinations of serum albumin level, peripheral total lymphocyte counts, total cholesterol levels, and anthropometric factors, such as body mass index, which are associated with nutrition and cancer progression." (PMID 34836339, 2021). "Therefore, we conducted this study using data from the Kailuan cohort to confirm and further evaluate the association between pre‐diagnostic serum albumin and cancer risk among Chinese." (PMID 34041866, 2021). "The exact cause of low albumin levels in patients with cancer is unclear." (PMID 33028394, 2020). "An increased vascular permeability with loss of albumin to the extravascular compartment might also contribute in cancer patients." (PMID 35847697, 2020). "Since a high-CRP level and a low-ALB level both have been found to be associated with poor survival in cancer patients, they might represent an aggressive propensity of the cancer and thus might serve as a factor for risk stratification." (PMID 31998420, 2020).
cancer (continued). "The serum albumin, has been found to be associated with poor survival outcomes in various cancers." (PMID 32087695, 2020). "Similarly, lower albumin levels symbolize insufficient nutritional and/or hypercatabolic states which result in weight loss and lowered BMI in cancer patients." (PMID 33082783, 2020). "Furthermore, it is recognized that an elevated CRP and low albumin concentration are risk factors for the development of cancer." (PMID 31487957, 2019). "However, reciprocally, patients primarily diagnosed with pancreatic “B/T” cancer are associated with much more pain, higher serum albumin level, higher carcinoembryonic antigen (CEA), and higher metastasis rate." (PMID 30965637, 2019). "As the brain, lung, liver, and bone are known organs prone to metastasis formation for many cancer types, we assessed these four organs for evidence of NETs deposition in our mouse models of albumin deficiency and oxidation (i.e., Alb−/− mice and IAA-injected Albwt/wt mice)." (PMID 30504805, 2018). "However, previously, in 10 studies, the cut-off point of 0.0300-0.6712 was used when examining the association between the CRP/ALB ratio with cancer outcomes in patients with solid cancers." (PMID 29495423, 2018). "Low serum albumin levels are reported to be associated with poor survival in several cancers." (PMID 30166572, 2018). "Serum albumin concentrations may be related to weight loss among patients with cancer due to changes in body mass and systemic inflammatory reactions." (PMID 29576961, 2018). "A number of studies have revealed that inflammation-based prognostic scores, such as Glasgow prognostic score (GPS), modified Glasgow prognostic score (mGPS), and C-reactive protein and albumin ratio (C/A ratio), are associated with poor outcome in cancer patients." (PMID 28740506, 2017). "Notably, clearance was higher in patients with low baseline serum albumin, which has been reported to be a risk factor for poor prognosis in patients with cancer." (PMID 27879974, 2016). "Moreover, we observed that low levels of hemoglobin and albumin were also associated with an increased risk of death by cancer." (PMID 25965806, 2015). "A combination of high sensitivity C-reactive protein (>3mg/l), albumin and neutrophil count predicted all-cause (HR 7.37, p<0.001, AUC 0.723), cancer (HR 9.32, p<0.001, AUC 0.731), cardiovascular (HR 4.03, p<0.001, AUC 0.650) and cerebrovascular (HR 3.10, p<0.001, AUC 0.623) mortality." (PMID 25730322, 2015). "In this study tumors that cause significant decline of mice body weight and serum albumin may account for the fact that human cancer wreaks havoc on man." (PMID 25797259, 2015). "Cancer-stage is an important confounder, probably linked to both weight loss and serum-albumin." (PMID 26148685, 2015). "Similarly, high levels of inflammatory markers and low hemoglobin value, which are usually associated with increased mortality, do not significantly improve the ability to predict survival better than cancer stage, albumin, and weight loss." (PMID 25400234, 2014). "It is also recognised that patients with cancer may have concurrent morbidity causing a rise in their C-reactive protein and derangement of their albumin and other biochemical parameters." (PMID 21266974, 2011). "Finally, in all 8 studies reviewed on patients with other cancer sites, lower levels of serum albumin were associated with poor survival." (PMID 21176210, 2010). "Accordingly, serum albumin level could be used in clinical trials to better define the baseline risk in cancer patients." (PMID 21176210, 2010). "There were similar interrelationships in the cancer cohort with the strongest associations (Spearman's correlation ⩾0.3) existing between C-reactive protein and albumin, C-reactive protein and Alk phos, bilirubin and AST, Alk phos and GGT, AST and ALT, AST and GGT and ALT and GGT." (PMID 20717110, 2010).
cancer (continued). "Finally, because low levels of serum albumin are associated with poor outcome in cancer patients, perhaps serum albumin can be used as an independent indicator of the need for aggressive nutrition intervention." (PMID 21176210, 2010). "When albumin was excluded from the multivariate analysis, only locoregional treatment (HR 8.85, 95% CI 2.85–27.41, P<0.001) and systemic treatment (HR 2.09, 95% CI 1.15–3.81, P=0.016) were independently associated with poorer cancer-specific survival." (PMID 18797461, 2008). "Longer LOS was associated with cancer, transferrin, IL-6 and albumin (p < 0.05)." (PMID 17505683, 2007). "Furthermore, albumin plays anti-inflammatory roles, which may influence the pathophysiology of cancers associated with systemic inflammation." (PMID 40427466, 2025). "However, hepatic dysfunction marked by elevated AST/ALT ratio (HR: 1.20, 95% CI: 1.05–1.36, p = 0.007) and metabolic disturbances including lower triglycerides, higher glycated albumin, and reduced lymphocytes were associated with cancer risk (all p < 0.05), requiring further validation." (PMID 40597094, 2025). "Albumin may assist in stabilizing cellular development and DNA replication, buffering various metabolic alterations, and preserving sex hormone balance to mitigate cancer risk." (PMID 41373357, 2025). "In fact, all components of HALP, hemoglobin, albumin, lymphocytes, and platelets, can be associated with the occurrence and prognosis of cancer patients, although the specific mechanisms of this association may vary depending on the type, stage of cancer, and individual patient differences." (PMID 39372874, 2024). "Given that low serum protein levels may predict inflammatory malnutrition, we aimed to assess the protein status of children with newly diagnosed cancer and the effect of pretreatment albumin and prealbumin deficiency on the incidence of infectious complications during treatment." (PMID 39619813, 2024). "Notably, cancer patients primarily use albumin-bound paclitaxel, and their underlying conditions (such as tumors) may themselves lead to certain adverse events." (PMID 39529884, 2024). "Fifth, cancer and immune disorders might also be the causes of increased non-albumin proteinuria." (PMID 38719892, 2024). "Poor diet, which is frequent in cancer patients, may also cause low albumin levels." (PMID 37438683, 2023). "Moreover, low serum albumin may mirror a poor performance status of cancer patients who are at increased risk of death." (PMID 38188302, 2023). "In addition to reflecting a person’s nutritional status to some extent, low albumin levels may increase the risk of malignant tumors due to poor nutritional status, but this is only a speculation and there is no relevant epidemiological study." (PMID 37836494, 2023). "On the one hand, albumin reflects the nutritional status of individuals, and in general, patients with poor nutritional status have a higher risk of postoperative complications, which may greatly shorten the survival time of cancer patients." (PMID 35571914, 2022). "A low albumin/globulin ratio may put patients at risk for cancer." (PMID 36547129, 2022). "ROS, ionizing radicals, and inflammation generated from radiation and chemotherapy mainly eradicate cancer cells and cause toxicity during the treatment course; thus, it is unclear whether exogenous antioxidants such as albumin and histidine improve or limit the overall treatment outcomes." (PMID 35804884, 2022). "Thus, inflammation induced by cancer may explain the observed associations between appetite and albumin, CRP, fatigue, and pain." (PMID 35629338, 2022). "Notably, serum albumin levels may reflect nutritional status and cancer treatment outcomes; changes in body cell mass and weight loss secondary to systemic inflammatory responses reduce serum albumin levels." (PMID 35975731, 2022).
cancer (continued). "Whether cancer cachexia is associated with changes in expression of the Fcgrt gene, which codes for FcRn, and/or the function of FcRn protein, thereby altering IgG and albumin CL is currently unknown." (PMID 34514376, 2021). "Albumin is a significant component of the plasma protein content and reflects the nutritional status, whereas lymphocytes reflect the immunological state; therefore, the ratio of serum albumin level to the lymphocyte count is associated with the survival of patients with cancer." (PMID 33482792, 2021). "However, evidence on serum albumin and cancer risk among the Chinese population is sparse." (PMID 34041866, 2021). "By extension, declining albumin may represent a loss of cancer control." (PMID 34660664, 2021). "Furthermore, it was proposed that serum albumin was a kind of endogenous antioxidant, which could reduce cancer risk through exerting anticarcinogenic properties." (PMID 34041866, 2021). "Therefore, the decreased ALB could reflect nutrient deficiency, which would lead to poor anti-cancer response and decline of immune function in cancer patients." (PMID 32822383, 2020). "HSA, like sTf, provides a source of selectivity towards cancer cells because the accelerated metabolism of cancer cells causes them to catabolize albumin as a nutrient source much more than normal cells do and this results in a greater interaction with and possible uptake of albumin." (PMID 34046448, 2020). "Using statistical analysis of whole-genome sequences across a diverse collection of cancers, they determined that other tumor types harbor similarly prevalent hotspots of noncoding somatic indel mutations, targeting lineage-defining genes (i.e., ALB, TG, and LIPF)." (PMID 30999697, 2019). "As for AGR, its relevance in cancer may be related to the antioxidative effects of albumin against carcinogens such as nitrosamines and aflatoxins, and the association of elevated globulin levels with the progression and metastasis of some cancers." (PMID 31444316, 2019). "On the other hand, a decreased serum albumin level partially reflects a malnutritional status in the host and weak human systematic defense, and thus, might be associated with increased morbidity and mortality of cancer." (PMID 29268783, 2017). "Furthermore, a wide array of hematological parameters that reflect the immune or nutritional status of organism have been identified to be associated with cancer prognosis, such as serum albumin, hemoglobin, lymphocyte, neutrophil and platelet, which are all readily available in clinical practice." (PMID 27765916, 2016). "GC is a chronic consumption disease and albumin might be catabolized caused by cancer progression." (PMID 26497995, 2015). "Here, by investigating how cancer cells overcome FcRn-mediated albumin recycling, we identify the Ras-Erk MAPK signaling pathway as a critical regulator of FcRn." (PMID 42056637, 2026). "The CALLY index, based on C - reactive protein, albumin, and lymphocyte levels, has shown potential in predicting cancer prognosis and guiding treatment." (PMID 41798270, 2026). "Drugs bound to albumin selectively target cancer cells with upregulated macropinocytosis, an endocytic nutrient‐scavenging process driven by constitutive hyper‐activation of the EGFR/RAS/PIK3CA signaling and Syndecan1 pathways." (PMID 41521502, 2026). "This receptor-mediated internalization ensures the selective delivery of albumin-bound therapeutics into cancer cells beyond what is afforded by the EPR effect alone." (PMID 41489768, 2026). "Drugs bound to albumin selectively target cancer cells with upregulated macropinocytosis, a process driven by constitutively hyper‐activated EGFR/RAS/PIK3CA signaling, which is common in HNSCC." (PMID 41521502, 2026). "At a protein level, DA: OA treatment played the dominant role, regulating metabolic, cancer and signalling pathways, including a large network centred around albumin and protein kinase activities." (PMID 41942899, 2026).